PML (PML nuclear body scaffold)
Diseases named in the same sentence as PML in open-access papers (continued):
Sharing a sentence is not in itself a finding about the gene and the disease.
cancer (continued). "Another link between cancer and PML became evident by comparing PML protein expression in normal and neoplastic human tissues." (PMID 29888200, 2018). "We also identified several cancer-related genes affected by SF3B1-associated abnormal splicing: NF1, PDS5A, DICER1, and PML." (PMID 30194306, 2018). "Together, these observations suggest that PML is a key regulator of self-renewal for some types of stem cells and stem-like cancer cells." (PMID 29416846, 2018). "Consistent with the mouse studies, low PML expression is observed in several types of human cancers, further supporting PML as a guardian to prevent tumorigenesis." (PMID 29416846, 2018). "The promyelocytic leukemia (PML) protein is an essential component of PML nuclear bodies (PML NBs) frequently lost in cancer." (PMID 28332630, 2017). "Arsenic causes cancer cell apoptosis by binding to protein kinase M2 (PKM2), located on the surface of PML/RARA." (PMID 29206204, 2017). "PML proteins have received much attention due to their pluripotent biochemical and physiological involvements in cancer, the immune system, and inflammatory conditions." (PMID 28525371, 2017). "Analysis of publicly available cancer data also revealed a significant correlation between PML and DDIT4 expression in several cancer types (e.g. lung, breast, prostate)." (PMID 28332630, 2017). "Other nuclear bodies, including the nucleolus and PML bodies, are also disrupted in cancer, with the specific aberration detected dependent on the type of cancer." (PMID 27507988, 2016). "PML plays important roles in cell cycle regulation, survival and apoptosis, and inactivation or down-regulation of PML is frequently found in cancer cells." (PMID 26539288, 2015). "At the age of 40 years and younger the cancer patients’ number of PML-NBs per cell increased after in vivo irradiation compared to the pre-existing PML foci (p = 0.15)." (PMID 24694011, 2014). "Lastly, I hope that collectively we will find pharmacological ways to modulate PML therapeutically for the treatment of cancer and other disorders." (PMID 24575390, 2014). "I therefore think that in the years to come PML research will pave the way to new discoveries and therapies for cancer and other diseases." (PMID 24575390, 2014). "In order to clarify the role of PML-NBs in the aging process, we examined peripheral blood monocytes of 134 cancer patients and 41 healthy individuals between 22 and 92 years of age, both before and after in vitro irradiation." (PMID 24694011, 2014). "We compared the pre-existing number of PML-NBs per cell in patients suffering from cancer and healthy controls." (PMID 24694011, 2014). "We evaluated the difference in patients’ PML response to stress factors like cancer and radiotherapy treatment dependent on age." (PMID 24694011, 2014). "In cancer cells the normal regulation of PML turnover is likely to become corrupted leading to destabilization of PML as a mechanism of evading tumor suppression." (PMID 23730625, 2013). "Then, the tumorigenic switch observed in cancer after loss of PML NBs might either be explained by primary alterations of SUMOylation homeostasis leading to secondary defects in NB-assembly or, alternatively, to altered global SUMOylation as a consequence of PML loss." (PMID 23847762, 2013). "Pertinently currently there are emerging several potentially druggable targets such as CK2, BMK1, KLHL20, and E6AP that has been demonstrated to negatively regulate PML stability in various pre-clinical cancer models." (PMID 23730625, 2013). "For example, treatment of cancer cells with etoposide triggers PML-induced senescence by engaging JAK/STAT pathway." (PMID 23730625, 2013). "Although ERK2 and Pin1 are frequently elevated in many cancers, the link to reduced PML levels in vivo is yet to be demonstrated." (PMID 23730625, 2013).
cancer (continued). "For example, IFNβ has been recently shown to induce cellular senescence, a key anti-cancer mechanism, via a PML-induced mechanism." (PMID 23730625, 2013). "It will also be important to understand PML function in the brain if new approaches to cancer treatment focus on activation of PML." (PMID 24062991, 2013). "As we have mentioned, in CML, a related but distinct cancer type, the PML protein is indispensable for quiescent LIC maintenance through the regulation of FAO by PPAR signaling." (PMID 23936764, 2013). "In this form of cancer, a chromosomal translocation results in a fusion protein containing PML and the retinoic acid receptor." (PMID 24062991, 2013). "While PML was initially studied in the context of cancer, it clearly has important functions in other cell types such as neurons." (PMID 24062991, 2013). "New exciting studies now link PML to the histone loading machinery, with implications for chromatin remodeling and cancer pathogenesis." (PMID 23760585, 2013). "The tailoring of PML therapies to target multiple defined genetic malfunctions in individual cancers offers an exciting novel approach to inhibit cancer cell growth." (PMID 23730625, 2013). "PML degradation induced by As2O3 (arsenic trioxide) treatment allows exit from quiescence and exhaustion of cancer stem cells (CSCs) in a murine model of the disease." (PMID 23847764, 2013). "Instead, transcriptional or post-translational regulation of PML expression and localization allows cancer cells to tune PML expression on the basis of the cellular context." (PMID 23936764, 2013). "This provides a rationale for a combination treatment of cancer cells with agents to stabilize PML such as emodin, XMD8-92, or anti-E6AP N-methyl peptide combined with DNA damaging agents and pro-senescence cytokines." (PMID 23730625, 2013). "The finding that PML expression is largely regulated in cancer cells at the level of proteasomal degradation triggered a search for the relevant E3 ligases that regulate the ubiquitination and subsequent degradation of PML in normal and cancer cells." (PMID 23730625, 2013). "Promyelocytic leukemia protein or PML exerts its anti-cancer role by modulating a number of pathways relevant to cancer biology." (PMID 23936764, 2013). "PML tumor suppressive functions have been validated in a number of genetically engineered mouse cancer models." (PMID 23730625, 2013). "Another key limitation in our understanding of PML is the shortage of information about isoform specific effects and the potential problem with protecting and activating cancer promoting or cancer suppressing proteins." (PMID 23730625, 2013). "Taken the rising importance of senescence, SUMOs, and PML in cancer genesis and also therapy response, exciting future developments are to be expected in this rapidly moving field." (PMID 23847762, 2013). "The significance of CK2-dependent PML degradation in cancer biology is highlighted by the finding that PML phosphomimetic mutant acts as a super tumor suppressor due to its prolonged half-life." (PMID 22935031, 2012). "When our manuscript was under review, we learned that two latest papers reporting PML’s role in cancer metabolism and stem cell metabolism." (PMID 22947142, 2012). "As our understanding of this event progresses, more specific inhibitors targeting a particular pathway will be discovered to antagonize a particular subset of human cancers displaying aberrant PML degradation." (PMID 22935031, 2012). "We believe that further study on PML and TNFα target genes will shed a light on specific molecular mechanisms of angiogenesis in cancer and human cardiovascular diseases." (PMID 22947142, 2012). "It is important to further elucidate the regulatory mechanisms of PML ubiquitination in human cancers." (PMID 22935031, 2012).
cancer (continued). "Here, we summarize our current understanding of the PML ubiquitination/degradation pathways in human cancers." (PMID 22935031, 2012). "Since ubiquitination is the major posttranslational modification that controls protein degradation through proteasome, identification of PML ubiquitin ligases would provide insights into the mechanism of PML regulation in human cancers." (PMID 22935031, 2012). "In viewing of the pleiotropic functions of PML in tumor suppression and its frequent degradation in various types of cancers, targeting the PML ubiquitination/degradation pathway becomes an attractive approach for anti-cancer therapy." (PMID 22935031, 2012). "Although aberrant regulation of some of these PML ubiquitination pathways has been observed in certain types of cancers, the prevalent PML degradation in cancers suggest the existence of additional ubiquitination pathways and/or regulatory mechanisms." (PMID 22935031, 2012). "The PML tumor suppressor protein is frequently downregulated in human cancers through a proteasome-dependent mechanism." (PMID 22935031, 2012). "In our study, we used wild-type PML and a PML mutant, in which the coiled-coil domain is deleted (PML C/C-), to investigate how these proteins can affect telomere maintenance pathways in cancer cells that use either the telomerase or ALT pathway." (PMID 22925423, 2012). "We discuss the potential of targeting PML ubiquitination pathways for anti-cancer therapeutic strategies." (PMID 22935031, 2012). "Cancer tissues were immunohistochemically stained for PML and IP-10, and the intensity of IP-10 immunopositivity was measured as described in Materials and Methods." (PMID 22022583, 2011). "We show that an increase in IP-10 levels in cancer cells expressing low levels of PML contributes to lymphocyte recruitment." (PMID 22022583, 2011). "For immunofluorescence (IF) microscopy studies, we selected Hep2 carcinoma cell lines because of their larger size and prominent PML nuclear bodies, and their common use in many previous studies with herpesvirus protein interactions with PML-NBs." (PMID 22102817, 2011). "It has become apparent that PML is an important contributing factor in the pathogenesis of malignant tumors." (PMID 19025608, 2008). "Loss of PML leads to the re-expression of transposable elements and the acquisition of 2-cell-like features via SUMO2 modification of DPPA2, illustrating PML’s critical role in coordinating stem cell states and its potential implications in cancer biology." (PMID 40442783, 2025). "In addition, PML-PMR have been found to be beneficial for patients with other types of cancer and chronic diseases." (PMID 40035884, 2025). "Notably, PML bodies are pan-cancer pleiotropic tumor suppressors that form phase-separated liquid-like condensates and are organized by multivalent interactions among proteins and RNA molecules." (PMID 38118002, 2024). "Cancer development has been closely linked with phase-separated macromolecular condensates, including stress granules, DNA repair condensates, PRC1 condensates, super-enhancer condensates, SPOP/DAXX bodies and PML puncta." (PMID 39358623, 2024). "Moreover, PML nuclear bodies regulate TNFα-induced cell death in cancer cells and suppress capillary tube formation and migration in endothelial cells." (PMID 38118002, 2024). "The PML gene is regulated in a highly tissue-specific manner in cancer." (PMID 38730056, 2024). "Moreover, PML depletion by gene knockout or arsenic trioxide treatment inhibited ALT induction in fibroblasts and ALT cancer cells, suggesting that APB formation underlies the orphan NR-induced ALT activation." (PMID 38752489, 2024). "PML protein is lost in human cancers of various histologic origins, including breast cancer." (PMID 37518985, 2023).
cancer (continued). "In addition, in cancer cells where an alternative lengthening of telomere (ALT) mechanism is active, BLM is associated with the ALT-associated PML NBs (APBs) and plays a critical role in ALT58." (PMID 37777511, 2023). "For these “high‐risk” subjects, preventive strategies such as careful monitoring of electrocardiogram and electrolytes, regular screening of cancer markers, imaging and endoscope, and close detection of the PML::RARα gene should be emphasized to allow early diagnosis and intervention." (PMID 37584196, 2023). "Moreover, deregulation of PML bodies leads to the activation of PPARδ mediated fatty acid oxidation pathways, which help in cancer stem cell maintenance, leading to disease progression and therapeutic refractoriness." (PMID 36142544, 2022). "Interestingly, SMC5/6 localizes at PML bodies in cancer cells (e.g. U2OS) that use the alternative lengthening of telomeres (ALT) mechanism to maintain their telomeres." (PMID 36373674, 2022). "For example, PML bodies have been shown to regulate aspects of cell growth, and the presence of these structures in mammals (i.e., mice) has furthered the exploration of the role of these structures in cancer." (PMID 36203874, 2022). "Because MYC, PML, and PHF8 have been implicated in human cancer metastasis, we investigated whether they were involved in CCL7 upregulation in OC-MQ." (PMID 34206004, 2021). "Although this finding needs to be verified through further extensive studies, we hypothesize that CTRP6 may attenuate PML protein-related fibrosis in cancer-stromal microenvironments." (PMID 33442414, 2021). "Moreover, our findings demonstrate that OGP46 induced cell differentiation and inhibited the colony-formation ability of these three cell lines through transcriptional misregulation in cancer pathway via depletion of PML-RARα in NB4 cells." (PMID 33748146, 2021). "It has been suggested that PML prevents cancer by inactivating nuclear AKT activity." (PMID 34215258, 2021). "Reduced levels of PML protein have been observed in human cancers of multiple origins." (PMID 34215258, 2021). "PML was also reported to be a tumor suppressor in many cancer types." (PMID 34625711, 2021). "Therefore, PML is related to the pathogenesis of a variety of cancers, including breast, stomach, prostate, lung, colon, and blood cancer." (PMID 35252219, 2021). "E6AP-mediated degradation of PML promotes tumorigenesis in multiple types of cancer." (PMID 32751183, 2020). "Thus, arsenic treatment induced degradation of YAP is likely to be mediated by the degradation of PML in ESCC cancer cells." (PMID 33353561, 2020). "Here, we speculated that HAdV mediated relocalization of PML‐NBs into tracks seems at a first glance similar to the PML‐NB microspeckled phenotype in APL cancer cells." (PMID 32328411, 2020). "Specifically, we asked whether ICP0-null HSV-1, which is unable to effectively infect cells with intact PML NBs, is able to infect and kill ATRX-deficient cancer cells." (PMID 30745338, 2019). "These contrasting activities may be essential in different cancer contexts that carry or evolve to different genetic and epigenetic background and may provide a mechanistic basis for the seemingly dual role of PML as tumor promoting or suppressing gene." (PMID 30927552, 2019). "Further analysis is required to precisely define the PMLIV‐specific transcriptomic or proteomic targets in different cancer genetic backgrounds that mediate its cell survival protective/suppressive role and may be counteracted by other PML isoforms." (PMID 30927552, 2019). "The dual role of PML in cancer under cell‐specific contexts is intriguing." (PMID 30927552, 2019).
cancer (continued). "SUMOylation was first associated with cancer not long after its discovery, with the identification of promyelocytic leukemia protein (PML) as one of the first known SUMOylation substrates." (PMID 30991648, 2019). "PML NBs are involved in the self-renewal of normal and cancer stem cells." (PMID 31635329, 2019). "A more precise determination of the relative PML isoform abundance in various clinical cancer datasets may help to better interpret the correlation of PML levels with patient survival that so far are based on total PML RNA levels." (PMID 30927552, 2019). "Previously it was shown that depletion of PML indeed decreases the ability to perform homologeous recombination (HR) repair, and it should also be mentioned that permanent lack of PML induces genomic instability and increased susceptibility to cancer." (PMID 29888200, 2018). "Overexpression of PML in cancer cell lines induces cell cycle arrest and apoptosis." (PMID 29888200, 2018). "We therefore provide an introductory overview on some imaging instrumentation which are covered by such facilities and provide specific examples in PML biology to encourage cancer cell biologists and biochemists to extend their experimental approaches toward the exciting new imaging technologies." (PMID 29888200, 2018). "Finally, our study provides a new context in which to view changes in PML expression during cancer development and progression." (PMID 28332630, 2017). "Therefore, we predict that PML and DDIT4 expression should be positively correlated, where cancer cells with low PML have low DDIT4 gene expression and vice versa." (PMID 28332630, 2017). "We then transduced epithelial carcinoma HeLa cells with the CAG or PML gRNA." (PMID 28656178, 2017). "On the other hand, based on its effect on promoting tumor progression by enhancing fatty acid oxidation, PML could also be a prognostic factor of cancers that undergo metabolic reprogramming." (PMID 27058621, 2016). "Importantly, PML inactivation in cancer cells can occur at the transcriptional-, translational- or post-translational- levels." (PMID 26539288, 2015). "Inactivation of PML in cancer cells occurs through multiple mechanisms." (PMID 26539288, 2015). "Inhibition of the proteasome pathway restores PML protein expression in select cancer cell lines." (PMID 26539288, 2015). "Clearly, the restoration of PML to inhibit cancer growth emerges as a promising targeted strategy that could be applied to many cancer types, given that PML plays a central tumor suppressive role in a wider range of human cancers than previously appreciated." (PMID 23730625, 2013). "It remains to be elucidated whether the function of the MCAF1/SETDB1 complex in PML bodies is separable from that in heterochromatin in cancer cells." (PMID 23935871, 2013). "In fact, when PML was knocked down in these cancer cells they lapsed into growth arrest." (PMID 23730625, 2013). "Two lines of evidence link PML and P21 activity in normal and cancer cells." (PMID 23847764, 2013). "In conclusion, PML has been revealed as friend and foe in cancer." (PMID 23936764, 2013). "In this respect, pharmacological degradation of PML via ATO treatment could represent a strategy to affect H3.3 loading in cancer cells." (PMID 23760585, 2013). "One noteworthy recent study, for instance, revealed that PML regulates the activation of fatty acid metabolism, and that this metabolic reprograming plays an essential role in cancer biology and stem cell biology through the control it exerts over stem cell fate decisions." (PMID 23504288, 2013).